EGFR (epidermal growth factor receptor)
Diseases named in the same sentence as EGFR in open-access papers (continued):
Sharing a sentence is not in itself a finding about the gene and the disease.
glioma (continued). "However, all attempts to improve the overall survival of glioma patients using EGFR inhibitors eventually failed." (PMID 36438805, 2022). "Moreover, EGFR amplification was found to be present solely in IDH wildtype gliomas (26%) and TERT mutated gliomas (27%), occurring independently of MGMT promoter methylation status and being mutually exclusive with 1p/19q codeletion (LOH)." (PMID 35453544, 2022). "We found that EGFR amplification is a phenomenon that predominantly occurs in high-grade glioma." (PMID 35453544, 2022). "The reason why N‐acetylgalactosaminyltransferase 2 (GALNT2) was closely associated with the migration and invasion of glioma cells is that GALNT2 facilitated the malignant features of gliomas by affecting the O‐glycosylation, EGFR phosphorylation, and subsequently the downstream PI3K/Akt/mTOR axis." (PMID 37786890, 2022). "Multiple mutations that coactivate the EGFR-Ras and PI3K-Akt pathways are required to cause glioma." (PMID 36003330, 2022). "This study utilizes the glioma cell lines that stably expressed the truncated EGFR (ΔEGFR)." (PMID 36199696, 2022). "In addition, PRKN inhibits glioma cell growth in vitro and in vivo by downregulating the intracellular levels of β-catenin and EGFR, leading to decreased activation of both Wnt- and EGF-stimulated pathways." (PMID 35832194, 2022). "Additionally, CRNDE promotes glioma cell growth through the enhancement of the activation status of the EGFR pathway." (PMID 35999564, 2022). "Interestingly, we found three commonalities for all analyzed glioma feedback regulators of the EGFR and FGFR signaling pathways: SPRY4, ERRFI1 and RAB31." (PMID 36231068, 2022). "GOLM1 promotes HCC, glioma and prostate cancer proliferation and growth through the regulation of the EGFR/PDGFRα/RTK signaling pathway, thus resulting in the activation of PI3K/AKT/mTOR signaling cascade and in the positive feedback loop, already described in the previous section." (PMID 35805075, 2022). "In contrast, EGFR mRNA expression in gliomas was higher than that in normal tissues." (PMID 35571034, 2022). "Mean EGFR gene amplification was 3 in CNS WHO Grade 4 gliomas using FISH." (PMID 35453544, 2022). "However, there are no published successful results indicating the relevance of PI3Kp110β inhibition in glioma cells or proposing EGFR/PI3K dual inhibitors." (PMID 35884571, 2022). "Moreover, lower DDR scores were observed in gliomas with IDH1 and ATRX mutations, but on the other hand, EGFR and PTEN mutations were associated with high DDR scores." (PMID 35720326, 2022). "Taken together, these results suggest USP6NL as an interesting potential to later predict EGFR overexpression or amplification in gliomas that may subsequently have a different phenotype than other glioma tumors." (PMID 35884836, 2022). "NEAT1 lncRNA is induced by the EGFR pathway in glioma which then sequesters the chromosome modification enzyme EZH2 to facilitate repression of certain target genes and to promote nuclear translocation of β-catenin, thus activating the WNT/β-catenin oncogenic pathway in GBM." (PMID 36009578, 2022). "Higher expression of Atoh8 was found to be correlated with the pro-neural group of gliomas particularly oligodendroglioma with ‘1p19q codeletion’ and lower expression of Atoh8 was found to be correlated with a proliferative and mesenchymal group of gliomas with ‘EGFR amplification’." (PMID 35053134, 2022). "For instance, a study conducted with the primary goal of identifying long non-coding RNA and clarifying its function and mode of action in glioma formation showed that LPP Antisense RNA 2(LPP-AS2) promotes glioma carcinogenesis through a miR-7-5p/EGFR/PI3K/AKT/c-MYC feedback loop." (PMID 35619711, 2022). "Analysis of TERT promoter mutation status and EGFR amplification showed that TERT mutated glioma show increased copies of EGFR using FISH and EPIC without statistical significance (p > 0.05, Student’s t-test)." (PMID 35453544, 2022).
glioma (continued). "Immunohistochemistry showed mean EGFR protein expression of 1 in CNS WHO Grade 4 gliomas." (PMID 35453544, 2022). "In this work, we identified GBP2/KIF22/EGFR as a potential therapeutic target for glioma." (PMID 35436989, 2022). "Perhaps a multi-faceted approach with both ErbB4 inhibitors and EGFR inhibitors could prove more consistently effective against high-grade gliomas." (PMID 36119496, 2022). "MiR-375 expression was significantly downregulated in gliomas; it could inhibit glioma growth by repressing the CTGF-epidermal growth factor receptor (EGFR) signaling pathway, thus inhibiting glioma proliferation, migration, and invasion." (PMID 35999601, 2022). "Furthermore, some of them have been proven to be drug targets in solid tumors, such as GPC3 in liver cancer, MSLN in gastric cancer, and EGFR in glioma." (PMID 36428765, 2022). "Moreover, inhibitions of EGFR are widely explored in gliomas like EGFR tyrosine kinase inhibitors and monoclonal antibodies, though few have excellent effects." (PMID 36338770, 2022). "Thus, via EGFR (vIII), glioma cell migration and survival are supported, as well as a change of the immunological state of TME in terms of a weakened proper immune response." (PMID 34687436, 2022). "This antagonistic relationship may indicate the necessity of combined c-Met inhibitions when considering giving anti-angiogenesis or anti-EGFR therapies for glioma patients." (PMID 36338770, 2022). "Similarly, our study indicated that silencing the KIF22 significantly suppressed the progression of glioma progression, and also impaired the protein expression and phosphorylation of EGFR." (PMID 35436989, 2022). "Alterations in metabolism-related genes, such as IDH1 mutation, O6-methylguanine-DNA methyltransferase gene (MGMT) promoter methylation, or epidermal growth factor receptor (EGFR) amplification, are frequent in glioma patients and are closely related to prognosis." (PMID 36248907, 2022). "An analysis of EGFR amplification and IDH mutation status revealed that IDH mutated glioma showed fewer copies of EGFR using FISH and EPIC without this being statistically significant (p > 0.05, Student’s t-test)." (PMID 35453544, 2022). "Successfully crossed the BBB and targeted gliomas, promoting the degradation of EGFR and p-EGFR." (PMID 35874843, 2022). "ASAP3 may be combined with EGFR to arouse NOTCH3 expression to promote adult glioma proliferation and invasion." (PMID 36382054, 2022). "The only fusion with a higher prevalence in OAs was intragenic fusions of EGFR in glioma." (PMID 36433963, 2022). "EGFR CNAs were evaluated in 39 of 60 glioma samples with a MAPD score <0.45." (PMID 35372034, 2022). "The experimental test beds used to confirm the results were: mouse glioma models obtained by retroviral expression of EGFR-wt/EGFR-vIII in primary progenitors from p16/p19 ko mice and grown in-vitro and in-vivo in orthotopic allografts, and human GBM U251 cells immobilized in alginate microfibers." (PMID 36325374, 2022). "Therapies targeting EGFR are promising methods for glioma treatment." (PMID 35874843, 2022). "It has yet to be explored whether CaCC inhibitors alongside EGFR-targeted therapy would be a promising combination therapy in glioma." (PMID 36497413, 2022). "EGFR overexpression has been detected in a significant proportion of head and neck, cervical, non-small cell lung, bladder, pancreatic and colon cancers, as well as in mesothelioma, glioma and other cancers, making EGFR a very attractive target for various anti-cancer agents in recent decades." (PMID 36432639, 2022). "Importantly, MMP9 seems to be transcriptionally regulated by EGFR signalling and involved in the regulation of key signalling pathways in glioma, such as PI3K/AKT, STAT3/5, NFkB, ERK, and SHH25–27." (PMID 36400876, 2022). "EGFR amplification was detectable in high-grade gliomas (25%)." (PMID 35453544, 2022).
glioma (continued). "Although the relationship between cuproptosis and EGFR remained unclear, more studies in this field might provide a novel direction for EGFR inhibitors’ application in glioma and overturn previous failures." (PMID 36267281, 2022). "At 5 days following implantation of 500,000 U87 human glioma cells in the caudate-putamen, mice were treated weekly by IV administration of (a) saline or (b) 5 μg DNA per mouse of HIRMAb/TfRMAb-THLs encapsulating the anti-EGFR shRNA expression plasmid." (PMID 35745855, 2022). "EGFR belongs to the ErbB receptor family and is one of the major factors in glioma tumorigenesis." (PMID 35888045, 2022). "Targeting these nanocarriers to common glioma-specific markers, such as Ephrin A2 (EphA2), epidermal growth factor receptor (EGFR), and others, might further improve personalized specificity and accumulation." (PMID 35999629, 2022). "Apparently, resistance to EGFR inhibitors in LGG patients has stimulated the development of multi-targeted or epigenetic agents or the use of combination drugs for the treatment of gliomas." (PMID 35572524, 2022). "Several EGFR TKI have been evaluated as possible treatments in patients diagnosed with glioma." (PMID 35267432, 2022). "Studies have revealed that several regulators take part in anoikis resistance in glioma; these include integrin, E-cadherin, EGFR, IGFR, Trk, TGF-β, the Hippo pathway, NF-κB, eEF-2 kinase, MOB2, hypoxia, acidosis, reactive oxygen species (ROS), heat shock proteins (Hsps) and protective autophagy." (PMID 36046036, 2022). "Through these pathways, EGFR can regulate anoikis resistance in gliomas." (PMID 36046036, 2022). "EGFR is a significant epigenetic and metabolic regulator in gliomas." (PMID 35681635, 2022). "Additionally, there are the infant-type hemispheric gliomas and diffuse-midline glioma epidermal growth factor receptor (EGFR) mutant." (PMID 35456430, 2022). "Recent recommendations from the cIMPACT-NOW consortium suggest that EGFR amplification and combined chr7 gain and chr10 loss as well as TERT promoter mutation can be used to diagnose IDH wild type (WT) grade II/III gliomas that are likely to follow a more aggressive clinical disease course." (PMID 35211690, 2022). "Within the IDH wild-type gliomas, EGFR amplification is related to a higher level of hypoxia." (PMID 35626127, 2022). "According to the gene expression, patients were categorized into two subgroups, and the patients with a higher SLC11A1 expression had a lower rate of IDH mutation and higher rates of EGFR and PTEN mutations, and which are considered to indicate a poor prognosis for glioma patients." (PMID 36531992, 2022). "Using FISH, we detected seven gliomas with EGFR amplification." (PMID 35453544, 2022). "The Epidermal Growth Factor Receptor (EGFR) is part of the broad group of receptor tyrosine kinases; according to The Cancer Genome Atlas (TCGA) data, alterations of EGFR gene are present in around 25% of gliomas: 54% of GBMs and 9% of lower grade gliomas." (PMID 35267432, 2022). "ER stress has a synergistic contribution to EGFR inhibitor gefitinib-induced apoptosis in glioma." (PMID 35887658, 2022). "The current study suggests simultaneous pH- and oxygen-sensitive amine CEST-SAGE-EPI is a clinically feasible and potentially valuable imaging technique for distinguishing glioma subtypes, revealing unique characteristics associated with IDH mutation, 1p/19q co-deletion, and EGFR amplification." (PMID 35626127, 2022).
glioma (continued). "Furthermore, gliomas were divided into “molecularly” low- and high-grade, based on the absence or presence of EGFR, H3F3A, or pTERT gene alterations; the first group showed a mOS improvement of about 6 months." (PMID 35756624, 2022). "Monovalent (EG2), bivalent (EG2-hFc), and pentavalent (V2C-EG2) nanobodies directed against the epidermal growth factor receptor (EGFR) and its variant III (EGFRvIII) have been successfully employed for in vivo fluorescence imaging of orthotopic high-grade glioma-bearing mice." (PMID 34439797, 2021). "Similarly, NPs made of lipid–poly(hypoxic radiosensitized polyprodrug), IO conjugated with epidermal growth factor receptor (EGFR), and RE have also been reported to enhance the sensitivity of radiotherapy in glioma cells by increasing the oxidative stress." (PMID 33738278, 2021). "Updated insights on EGFR signaling pathways in glioma have recently been reviewed." (PMID 34209513, 2021). "Similarly, IDH-wild-type gliomas with EGFR amplifications and/or chromosome 7 amplifications and chromosome 10 loss can be molecularly defined as GBM, conferring worse prognosis." (PMID 33622343, 2021). "And a combination of BRAFV600E inhibitors and pharmacologic inhibition of EGFR could greatly improve the efficacy by decreasing glioma cell proliferation and promoting apoptosis." (PMID 34482648, 2021). "Thus, we first investigated the relationship between EGFR expression and the survival of glioma patients using the REMBRANDT database of the United States National Cancer Institute." (PMID 34495991, 2021). "GISTIC 2.0 analysis revealed that in gliomas with high-risk scores, the amplification mainly occurred in chromosomal regions 1q32.1, 3q26.33, 4q12, 7p11.2, and 12q14.1, where several key oncogenes (PDGFRA, EGFR, MDM2, SOX2, and CDK4) were located." (PMID 35116021, 2021). "We thus speculate once more that targeting endocytosis by p38 inhibition would reduce Rab5-mediated EGFR endocytosis and increase glioma cell resistance to gefitinib as has been found in the case of cisplatin treatment of U87 cells." (PMID 34831480, 2021). "However, EGFR inhibition has been observed to enhance the chemo- and radiosensitivity of human glioma CSCs." (PMID 33762015, 2021). "Furthermore, EGFR is required for the maintenance of glioma growth; and the EGFR pathway participates in several cellular responses, such as proliferation, migration, cell differentiation, as well as in stability of the intracellular environment." (PMID 33407703, 2021). "In addition, the amplification frequencies of LANCL2 and EGFR in GBM were six to nine times higher than those in grade II-III gliomas." (PMID 34461927, 2021). "Besides EGF/EGFR signaling, current findings are consistent with the ROS/ER stress axis likely being a target for the anti-glioma actions of gefitinib." (PMID 33920356, 2021). "Several studies have revealed the convergence of EGFR and Wnt signaling through a reciprocal regulation at transcription as well as posttranscriptional level and suggested their collaborative contribution to the poor prognosis of glioma." (PMID 34540693, 2021). "Interestingly, the combination of TBR/ADC had a significantly higher diagnostic accuracy than that of each single imaging method in both glioma grading and predicting the mutation status of IDH1, hTERT, and EGFR." (PMID 34912706, 2021). "Compound 10, the most potent anti-glioma agent in this series, underwent further mechanistic studies, including the determination of apoptotic induction and inhibitory effects on a large panel of tyrosine kinases, particularly EGFR." (PMID 34681605, 2021). "These gliomas may have EGFR alterations, which are also considered independent drivers of gliomagenesis, TERT promoter mutations, chromosome 7 gain, and chromosome 10 loss." (PMID 34356864, 2021). "In addition to invasion and migration, glutamate stimulates tumor growth, proliferation, and survival of glioma cells through the EGFR-phospho-Akt and PI3K/AKT pathways." (PMID 34149360, 2021).
glioma (continued). "BCAR4 promoted glioma cell progression by stimulating the EGFR/PI3K/AKT pathway." (PMID 34178684, 2021). "Indeed, microglia can stimulate the invasion of glioma cells, and this is partially dependent on EGFR activation." (PMID 34830952, 2021). "Moreover, we found significantly higher EGFR expression in patients with E1- and E2-amplified glioma." (PMID 33537074, 2021). "Over the past decade, many drugs have entered clinical trials for treatment of gliomas including epidermal growth factor receptor (EGFR) targeted therapies, protein kinase B (Akt) inhibitors, mutant isocitrate dehydrogenase (IDH1) inhibitors and calcium channel inhibitors." (PMID 33404912, 2021). "We hypothesized that development of glioma is repressed by AZD3759 through the inhibition of the EGFR and JAK pathways." (PMID 34635007, 2021). "The findings suggest that ER-stress-based therapeutic targeting could be a promising option in EGFR inhibitor glioma therapy, and may ultimately achieve a better patient response." (PMID 33920356, 2021). "We hypothesized that AZD3759 inhibits the development of glioma by repressing the EGFR and JAK pathways." (PMID 34635007, 2021). "Similarly, glioma samples harbouring rearrangements near the commonly hyper-amplified EGFR showed up-regulation of the surrounding locus." (PMID 34891161, 2021). "To test whether TRAF2 can regulate the stability of EGFR in glioma cells, we performed knockdown of DYRK1A and TRAF2 in human glioma cell lines U251 and A172, and analyzed the protein level of EGFR." (PMID 34117217, 2021). "Expressed as cell-surface receptors in many cancers including gliomas, epidermal growth factor receptor (EGFR) may be conjugated with fluorescent dyes, allowing for targeted cell-surface fluorescence." (PMID 34220688, 2021). "Finally, a correlation between YTHDF2 protein expression and the expressions of p-EGFR (Y1173), p-Src (Y419), and p-ERK1/2 in human gliomas also suggested the importance of this EGFR/SRC/ERK/YTHDF2 cascade in tumor development." (PMID 33420027, 2021). "One hundred and sixty-one glioma patients had both EGFR and CDKN2A alterations." (PMID 33959491, 2021). "EGFR and epidermal growth factor variant III (EGFRvIII) cooperate to induce macrophage infiltration via upregulation of the chemokine CCL2, and KRAS was a critical signaling intermediate for the EGFR- and EGFRvIII-induced expressions of CCL2 in glioma cells." (PMID 34071306, 2021). "Novel pathogenesis-based treatments targeting oncogenic signaling pathways such as BRAF mutation, epidermal growth factor receptor (EGFR) amplification, and fibroblast growth factor receptor (FGFR)-TACC fusion demonstrate a potential for lower grade gliomas (LGG) elimination." (PMID 34805164, 2021). "The EGFR gene was frequently affected by CNA—altogether in 554 (74%) glioma samples." (PMID 34209611, 2021). "EGFR is observed to be overexpressed in 30–40% of higher grade glioma patients." (PMID 34495991, 2021). "Notably, MYC can bind to the EGFR/EGFRvIII promoter region to increase the malignant phenotype of glioma cells." (PMID 34646821, 2021). "Interestingly, crosstalk between integrins and growth factor receptors, including EGFR, has been largely described in several solid tumors, including glioma." (PMID 34577582, 2021). "Although many molecular biomarkers are linked to glioma, such as isocitrate dehydrogenase enzyme 1/2 (IDH1/2) mutation and epidermal growth factor receptor (EGFR) overexpression, their reliability and clinical significance are still controversial and need more research." (PMID 34222249, 2021). "EGFR amplification is observed in the classical subtype of glioma." (PMID 33435537, 2021).